EGFR (epidermal growth factor receptor)
Diseases named in the same sentence as EGFR in open-access papers (continued):
Sharing a sentence is not in itself a finding about the gene and the disease.
tumor (continued). "It is noteworthy that the saturation of EGFR mediated endocytosis in normal tissues did not predict the saturation in tumor tissue as the local antibody concentrations in EGFR-overexpressing tumors may be more rapidly reduced by antibody internalization." (PMID 23840214, 2013). "A previous study revealed four important cancer invasion-related genes, MMP-1, MMP-2, EGFR and COX-2, in a variety of human cancers, including GC, which may manipulate the migration of tumour cells and the formation of new tumours by facilitating the release of tumour cells into the circulation." (PMID 23833643, 2013). "Similarly, in our present experiment, upon intraperitoneal injection and complexing of LPEI EGFR-specific siRNA (0.8 μg) induced a marked down-regulation of EGFR expression in NSCLC xenografts, also resulting in significant tumor growth inhibition by repeated treatments noted after 3 weeks." (PMID 27234384, 2013). "Expression of dominant-negative EGFR protein was verified by western blot of tumor tissue." (PMID 23429996, 2013). "However, the treatment effects of TKIs in patients who show a different subcellular distribution of EGFR in tumor cells have not been well investigated yet." (PMID 23536868, 2013). "Potentially, the addition of a mithramycin regimen may be beneficial to patients with wild-type EGFR to become sensitized to platinum treatment through inhibition of EPS8 and downstream targets which play a large role in tumor cell proliferation, adhesion and motility." (PMID 24367505, 2013). "However, their role was revolutionised by the discovery that patients whose tumours harbour mutant forms of KRAS do not respond to anti-EGFR therapy." (PMID 23356214, 2013). "While this does not prove that EGFR pathway engagement was the mechanism of resistance in this patient, it does suggest that EGFR activity was sufficient to induce resistance to crizotinib in the patient’s tumor cells." (PMID 24349229, 2013). "Moreover, under high EGF concentrations, tumor cells did not retain EGFR amplification and lost tumorigenicity in vivo." (PMID 24294177, 2013). "We present here the final results of the irinotecan versus IrPan comparison for patients with KRAS wild-type tumours who had not received previous anti-EGFR therapy; findings from the irinotecan versus irinotecan plus ciclosporin comparison will be reported elsewhere." (PMID 23725851, 2013). "Analysis of five LADC cases of never-smokers without EGFR/KRAS/ALK alterations using transcriptome sequencing identified 56 reads overriding the in-frame EZR-ROS1 gene fusion point connecting EZR exon 10 to ROS1 exon 34 in one tumor." (PMID 23418494, 2013). "Specific binding of GrB-T from NKL/GrB-T cells and high and selective cytotoxicity in the presence of chloroquine was also observed for other EGFR-overexpressing tumor cells such as A431, confirming that these effects are not restricted to MDA-MB468 target cells." (PMID 23573299, 2013). "However, the functions of the whole gene deletion of EGFR or the single exon copy number amplifications in tumor cells were not evaluated." (PMID 24205362, 2013). "In our study, pTyr1068 expression had a weak correlation with EGFR mutation and patients with pTyr1068 expression possessed a better response and prolonged PFS to EGFR-TKIs therapy, whereas pTyr1173 positive tumor was not correlated with EGFR mutation and had poor outcome to EGFR-TKIs therapy." (PMID 22901364, 2012). "In non-tumor tissue, we found no or very weak EGFR expression whatever the antibody used." (PMID 22159595, 2012). "With the knowledge that genetic background and diet differentially influence tumor incidence, it is reasonable to expect, albeit not yet tested, that they may also be important factors contributing to the variability of EGFR-targeted therapies." (PMID 22761823, 2012).
tumor (continued). "The numerous signaling cascades that radiate from EGFR, including the Akt, extracellular signal regulated kinase (ERK) 1/2, and signal transducer and activator of transcription (STAT) 3 pathways, mediate a variety of mitogenic, metastatic, and other tumor-promoting cellular activities." (PMID 22761867, 2012). "Cetuximab effect in inhibiting this pathway was shown to be in tumors expressing wild-type EGFR and not EGFRvIII, thus proving that expression of EGFRvIII on tumor cells might result in resistance to cetuximab." (PMID 22778735, 2012). "We cannot exclude the possibility that EGFR/Ras signaling may ultimately have some significant predictive value for reovirus therapy in SCCHN, especially in the light of the extensive interconnectivity and redundancy of signaling pathways within tumour cells." (PMID 22920673, 2012). "In addition to blocking downstream EGFR signaling pathways crucial for tumor survival, cetuximab also stimulates antibody-dependent cellular cytotoxicity (ADCC) by recruiting activated immune cells into tumors to augment tumor cell killing." (PMID 23150825, 2012). "Second, the classification of tumor subtypes as defined in our study is not identical to other published data due to the lack of information on other tumor markers, such as cytokeratin (CK) 5/6 expression, epidermal growth factor receptor (EGFR), and Ki67." (PMID 23350064, 2012). "The role of tumour K-ras and EGFR status was not known at the time of study inception and is a factor, which may have influenced clinical outcomes." (PMID 22315057, 2012). "However, the linearity of the EGFR expression by tumor cells response to As2O3 therapy is not clear and will require further study to elucidate." (PMID 23029451, 2012). "Though some HE gene modifications, such as insertions of small peptide ligands and terminal extensions with the anti-EGFR scFv425, could be incorporated into the viral genome, the resulting recombinant viruses were unable to redirect MHV to human tumor cells (Verheije and Rottier, unpublished data)." (PMID 22312365, 2012). "By comparison of normal and tumor expression of EGFR mRNA and protein at a ratio of 2.0 as a cutoff point, we found that expression of EGFR mRNA and protein was significantly increased in NSCLC tissues compared the non-tumor tissues (P = 0.024 and P = 0.008, respectively)." (PMID 22537942, 2012). "Loss of PTEN expression was also correlated to an increased gene copy number of EGFR, because 45.5% (15 out of 33) of the tumours with a CNG of EGFR presented a negative PTEN expression in comparison with 16.4% (30 out of 83) PTEN negativity in tumours without a CNG of EGFR (P=0.001)." (PMID 22240798, 2012). "Therefore, a logical strategy for improving anti-tumor efficacy is inhibition of both VEGFR and EGFR signaling pathways, which may help increase suppression of oncogenic processes involved in disease progression." (PMID 22916093, 2012). "Interestingly in a small study of 43 patients with K-Ras wild-type CRC, the 7 patients with high tumour budding had no response to EGFR-targeting therapies." (PMID 22991509, 2012). "Circumstances where AG1478 reduces EGFR signal but not tumor growth may indicate the presence of EGFR-independent tumors." (PMID 22761823, 2012). "Finally, there were no data on CK5/6 and EGFR tumor markers to further classify TN cases into basal-like and unclassified." (PMID 23181105, 2012). "There is a growing appreciation that EGFR signaling in epithelial cancer cells stimulates the expression of many chemokines, cytokines, growth factors, and receptors that facilitate paracrine interactions with non-cancer cells of the tumor microenvironment." (PMID 22276166, 2012). "However, despite this progress in anti-EGFR based cancer treatments, they lack of tumor-specific delivery, which should result in inefficient anti-tumor activity." (PMID 22355336, 2012).
tumor (continued). "In addition, the SRM assay was applied to a collection of histologically-characterized FFPE NSCLC patient tumor tissue where EGFR levels were quantitated from not detected (ND) to 670amol/μg." (PMID 22554165, 2012). "However, the in vivo therapeutic effect of As2O3 on EGFR expression of OSCC tumor xenografts has not been reported." (PMID 23029451, 2012). "Increased EGFR expression was found in 15% tumours (21/141) and correlated with high mitotic index (P=0.013) and negative HR (P<0.000), and there was a trend towards higher tumour grade (P=0.061)." (PMID 22454081, 2012). "Inter-observer variability in the definitions of the expression EGFR may depend on the tissue fixation technique used, possibly leading to false negative samples by IHC using paraffin-embedded tumor tissues." (PMID 22043994, 2012). "Ampligen® targets EGFR and very effectively destroys EGFR-overexpressing tumors with no adverse or toxic effects, suggesting that tumor therapeutics might be possible with TLR ligands." (PMID 23151919, 2012). "Thus, shifting the tumor suppressor/oncogenic balance toward oncogenesis by constitutive EGFR activation allows for malignancy, but not a robust metastatic phenotype due to continued metastasis suppressor signaling by TGFβ." (PMID 22672900, 2012). "The expression level of EGFR on tumour cells was not correlated with therapeutic response." (PMID 22152101, 2011). "In the clinic this has been exemplified by tumours that acquire mutations of BCR-ABL, KIT, PDGFR and EGFR during treatment, where the mutated proteins are no longer susceptible to inhibition by the targeted agent, but retain enzymatic activity and the ability to promote cell growth and survival." (PMID 21649578, 2011). "Immunohistochemistry has a central role for the diagnosis of SCCB through the staining of tumour components by antibody markers targeting the following antigens: neuron-specific enolase (NSE), chromogranin, synaptophysin, serotonin, cytokeratin, S-100 protein, TTF1, EGFR and C-KIT." (PMID 22078012, 2011). "Additionally, responses to anti-EGFR therapy seem to be independent of EGFR expression on the surface of tumor cells." (PMID 21970318, 2011). "However, the potential anti-tumor effect of curcumin combined with EGFR-TKIs on NSCLC has not yet been investigated." (PMID 21858220, 2011). "Although it has been well recognized that EGFR mutation is strongly associated with the therapeutic effect of TKIs in NSCLC patients, most patients could not provide the tumor tissues that needed for the mutation test." (PMID 22142557, 2011). "It was hypothesized that the dosage of anti-EGFR inhibitors may not have saturated the receptor in high expressing tumours and further studies are warranted." (PMID 22091418, 2011). "Since the discovery of the benefit of EGFR-targeted monoclonal antibody therapy in patients with KRAS wild-type metastatic colorectal cancer, it has become increasingly important to understand the mechanisms operating in tumours that eventually develop drug resistance." (PMID 21811251, 2011). "And while it has been shown that EBP50 can cluster with EGFR, PDGFR, and the tumor suppressor NF2 to halt cell signaling and hence cancer progression, others have posited that EBP50's PDZ domains may actually allow for new tumor-specific interactions." (PMID 21672215, 2011). "Over expression of EGFR leads to receptor clustering in the cell membrane which makes a cell hyper-sensitive to EGFR substrates; this aids the survival of MDR cells, especially hypoxic tumor regions that may be distal from a continuous nutrient supply." (PMID 21931642, 2011). "Thus, preferential sites of EGFR-mutant tumors, rather than tumor extent, were suggested in this study." (PMID 22091430, 2011).
tumor (continued). "Beyond the investigation of the EGFR gene, our method can be adapted to assess other molecular targets (e.g. HER2), and to analyze cancer cells in other cytological samples, where the low percentage of tumor cells limits the genomic analyses by current methods." (PMID 22140428, 2011). "Our observations of variation in the uptake of 11C-erlotinib further suggest that not all tumours in the same patient are driven by EGFR signalling, and therefore may not respond to erlotinib treatment." (PMID 22095231, 2011). "However, not all patients with KRAS WT tumours benefit from anti-EGFR moAbs treatment, meaning that additional genetic determinants of resistance exist." (PMID 21283802, 2011). "Consequently, the heterotopic or orthotopic models from human GBM cell lines do not recapitulate an extremely important aspect of tumor invasion and EGFR gene overexpression, which has somewhat limited its application in clinically relevant researches." (PMID 21314332, 2011). "None of p-EGFR, p-Akt, or p-Stat3 were seen in tissue adjacent to the tumor or normal skin." (PMID 21197106, 2011). "Precise mechanisms by which anti-EGFR antibodies may radiosensitize tumor cells are not fully understood, but their ability to target the CSC population is one likely mechanism." (PMID 24212957, 2011). "Thus, the impairment most likely accounting for the insufficient EGFR-specific immune response in HNSCC patients might be related to the dose of antigen and tumor-derived immune suppression." (PMID 21970318, 2011). "The trial was not limited exclusively to patients with EGFR FISH positive tumours." (PMID 21654681, 2011). "However, the expression level of EGFR on tumour cells per se, as determined by immunohistochemistry, was not predictive of therapeutic response in gastric and OGJ cancer in various phase II trials of cetuximab in combination with chemotherapeutic agents." (PMID 22152101, 2011). "However, the lack of availability of tumour tissue post treatment for validation of target inhibition results in uncertainties regarding the sufficient inhibition of the EGFR signalling." (PMID 20515495, 2010). "Although EGFR overexpression has been reported to be a hallmark of OSCC, investigations on Her-2 in OSCC have described protein overexpression in a very few tumour specimens, which did not appear to be of prognostic relevance." (PMID 20429940, 2010). "EGFR and Her-2 were not considered to be valuable salivary tumor markers in OSCC, however, lower levels of EGF in saliva may suggest a higher susceptibility for OSCC development." (PMID 20429940, 2010). "However, from EGFR copy number analysis in each component of the tumor, no EGFR amplification was found." (PMID 20961443, 2010). "In tumor cells EGFR expression was found by IHC in 7 from 9 patients without gene amplification." (PMID 20565817, 2010). "High expressions of EGFR, HER-2 and HER-4 were observed in 25 (39.7%) of 63, 26 (41.3%) of 63 and 31 (49.2%) of 63 tumours, in which 48.0% (12 out of 25), 61.5% (16 out of 26) and 54.8% (17 out of 31), respectively, exhibited heterogeneous expression within tumours." (PMID 20664599, 2010). "EGFR amplification was absent in anal canal tumours (0/23), but could be identified in 4 of 24 tonsil tumours." (PMID 20459770, 2010). "Since inhibition of EGFR and HER-2 has been shown to reduce angiogenesis through an indirect effect on VEGF production, we evaluated whether lapatinib interferes with tumor angiogenesis in the A549 model in vivo." (PMID 20459769, 2010). "Expansion efficiency, NK receptor repertoire before and after expansion, expression of NK specific ligands, cytolytic activity against allogeneic and autologous tumor targets, with and without the addition of chimeric EGFR monoclonal antibody, were investigated." (PMID 20937115, 2010).
tumor (continued). "Epidermal growth factor receptor protein expression is no longer considered as selection criteria for cetuximab sensitivity, and the mechanism of cetuximab's anti-tumour activity remains a fundamental question to be clearly addressed." (PMID 19953097, 2010). "Although totally 16 changes were observed in the present study, switch from positive EGFR expression in the primary tumor to negative in the metastatic site was observed only in 2 cases (4.2%, 2/47) and negative to positive EGFR conversions occur less than 6.5% of the cases (3/47)." (PMID 20096104, 2010). "In support of this hypothesis, two recent studies showed that cancer patients with tumours expressing either AR or EPI have a better response to treatment with EGFR-targeting drugs compared with patients with tumours not expressing AR or EPI." (PMID 19531065, 2009). "A total of 56 molecules are annotated as affecting neoplasia and eight of these are dysregulated over 1.5 fold in Ad12-TC compared to Ad5-TC: down-regulation of ATM, CD19, CD3G, GADD45B, HPSE, TFAP2A and TFPI was observed, whereas levels of EGFR were found to be up-regulated." (PMID 19200380, 2009). "Because EGFR inhibition can downregulate HIF-1α expression in tumor cells and decrease VEGF secretion, we hypothesized that erlotinib treatment would indirectly lead to vascular normalization and decrease tumor hypoxia." (PMID 19657384, 2009). "Importantly, however, EGFR receptor expression levels when assessed by IHC have not been able to predict a response to EGFR inhibitors in other tumour types." (PMID 19088718, 2009). "Moreover, the combination reduced VEGFR2 and EGFR protein expression in neoplastic endothelia but not tumour cells." (PMID 19830244, 2009). "However, in most of these trials, expression levels of EGFR in the tumor have not correlated with response to cetuximab and no single biomarker to date in baseline tissue has been proven to predict response to EGFR targeting agents." (PMID 19636423, 2009). "The anti-EGFR antibody induced by Sec-N'-EGFR DNA played a role in delay tumor progression although the amount of antibody may not be correlated with antitumor effects of three forms of therapeutic EGFR DNA vaccine." (PMID 19178753, 2009). "Augmented EGF signaling to Rho mediated by clustered EGFR may have relevance to chemotaxis and directed motility of nonadherent (circulating) or less adherent (migrating) tumor cells." (PMID 19470173, 2009). "K-RAS gene mutations on codons 12, 13, and 61 result in constitutive activation of the RAS protein, which may render tumor cells independent of EGFR signaling and also resistant to anti EGFR therapy." (PMID 19159467, 2009). "EGFR levels in the tumour do not appear to correlate well with clinical efficacy." (PMID 19531065, 2009). "We hypothesize that tumor cells in nonadherent or less adherent conditions, such as circulating or migrating tumor cells, might selectively regulate EGFR to enhance chemotaxis or motility at the expense of growth and survival signaling." (PMID 19470173, 2009). "However, there was negative correlation with CCHCR1 and EGFR expression in these same cell lines as well as in invasive FaDu tumor cells, suggesting that EGFR transcription was inhibited." (PMID 19551138, 2009). "Considering the fact that cetuximab is a monoclonal antibody that specifically targets EGFR and competitively inhibits ligand binding, it is not unexpected that the patients with tumour expression of EGFR and low levels of competitive ligands showed better treatment outcome." (PMID 19127259, 2009). "In contrast to IHCC, EGFR expression was not an independent prognostic factor in EHCC, but was associated with clinical features that may represent tumour progression and invasion, such as lymph node metastasis and apparent stromal invasion in EHCC." (PMID 18087285, 2008).